IL1B (interleukin 1 beta)
Diseases named in the same sentence as IL1B in open-access papers (continued):
Sharing a sentence is not in itself a finding about the gene and the disease.
infection (continued). "Increases in GM-CSF, IL-1β, and KC levels were observed only in αβR−/− λR−/− mice upon infection, but the concentrations were not significantly different from those observed in αβR−/− mice following infection." (PMID 28811340, 2017). "Besides, the IL-1β expression level at 6, 24 and 48 hpi, and IL-18 expression level at 6 and 24 hpi were all significantly increased during SCAU-HN06 infection." (PMID 29245947, 2017). "Indeed, the levels of INF-γ, IL-1β, IL-5, IP-10, MCP-1, and MIG were elevated in the mice given the mixed-infection at a 1:10 ratio compared with those infected with YM alone." (PMID 28790316, 2017). "IL-1β, IL-6, and TNF-α are proinflammatory cytokines released by activated macrophages, are involved in the upregulation of inflammatory reactions, and are important contributors to the inflammatory response to infection." (PMID 28255203, 2017). "Taken together, our data provide strong evidence that the responses mediated by DCs, Mo/Mφ, NK and CD8+ T lymphocytes through IL-1β, iNOS and granzyme B production, respectively, together with the production of type I IFN early in the infection, are crucial to host defense against HSV-1." (PMID 28222752, 2017). "Infection of RAG mice with L. braziliensis did not change the expression of pro-IL-1β in the skin, suggesting that parasites alone do not induce pro-IL-1β expression at the infection site." (PMID 28192528, 2017). "Multiple inflammatory cytokines, including TNF-α, IL-6, IL-1β, IFN-γ, IL-17, and VEGF, disrupt BBB and TJ integrity in BMECs, and inflammatory cytokine signaling at the BBB during infection facilitates leukocyte trafficking into the CNS, which is essential for the clearance of many pathogens." (PMID 29403485, 2017). "Knockdown of salusin-β with Ad-Salusin-shRNA dose- and time-relatedly reduced salusin-β, IL-1β, IL-6 and TNF-α mRNA levels, and NOX2 protein and 4-HNE levels in HG-treated H9c2 cells, reaching its maximal effects at the multiplicity of infection (MOI)=100 treated for 24 h." (PMID 28333148, 2017). "In comparison with wild-type bacteria, infection with the complemented PA14 ΔflgK pUCP19-flgK and PA14 ΔpopB pUCP19-popB strains restored to varying degrees the protein levels of TLR4, TLR5, NLRC4, caspase-4 and mature IL-1β and IL-18." (PMID 28469996, 2017). "Otherwise, IL-1β RNA expression was slightly increased in hCFs-siTLR5 infected with the PA14 ΔflgK mutant compared to no infection." (PMID 28469996, 2017). "Hyphae cell infection resulted in IL-1β secretion, while conidia failed to induce significant levels of this cytokine." (PMID 29209318, 2017). "Infection with wild-type PA14 induced intracellular IL-1β protein production, which was not inhibited by MyD88i or TAK-242." (PMID 28469996, 2017). "All media samples from mock-infected and infected biopsies collected at −4 h mock infection and 4 h after infection (4 h of accumulation) were negative or showed very low concentrations of IL1β." (PMID 28959685, 2017). "Hence, we saw an increase in the inflammatory cytokines IL-1α and IL-1β and also MIG was increased in the early part of the infection in extracts from both strains of mice." (PMID 28235018, 2017). "Interestingly, in an EV-A71 infection mouse model, viral proteases were able to overcome the effects of NLRP3 inflammasome activated IL-1β leading to increased viral replication." (PMID 28724943, 2017). "After 6 h of hCFs infection with wild-type PAO1 and PA14, significant levels of TLR4, TLR5, NLRC4, native form of caspase-4 and IL-1β and IL-18 mature-formed proteins were detected by western blot with quantification of protein densitometry ratios relative to endogenous β-actin." (PMID 28469996, 2017). "In contrast, Breyne and co-workers (2015) reported that infection of the mouse mammary gland with S. aureus resulted in local induction of IL-1β and IL-6 but not TNF-α." (PMID 28129375, 2017).
infection (continued). "Because CO is able to inhibit TLR4 signaling and because KSHV infection activates TLR4 signaling, we next tested whether the expression of IL-1β and IFNβ in KSHV-infected iLEC could be reduced by delivering CO to iLEC immediately prior to infection." (PMID 28421060, 2017). "Concerning inflammatory cytokines, the expression of IL-1β was not modulated in presence of iPPVO after infection with EHV-1 or EHV-4." (PMID 28925977, 2017). "IL1β which mediated AMP-expression, is increased in the airways during active TB; and may already be elevated early after Mtb-infection of alveolar macrophages before the onset of detectable lung pathology." (PMID 28863187, 2017). "ΔN146-infected cells, similar to the LPS-treated cells, expressed and secreted copious levels of type I interferon β (IFN-β), IL-1β, IL-6 and tumor necrosis factor α (TNF-α) 12 h post infection whereas these cytokines were barely detectable in supernatants from mock infected cells." (PMID 28150813, 2017). "Our results are in accordance with others, which have reported that BTV-1 primary infection triggered IL-1β expression but BTV-8 inoculation failed to induce the production of this cytokine." (PMID 28662714, 2017). "Therefore, the expression of IL-1β, IL-18, NLRP3, Caspase-1, ASC, and Syk mRNA was characterized in lung macerates of WT, Nlrp3−/−, Casp1/11−/−, and Asc−/− mice at week 4 after infection." (PMID 28740491, 2017). "The production of IL-1β and TNF, as well as the expression of inducible nitric oxidase synthase (iNOS), were also downregulated post-infection in vivo." (PMID 28824166, 2017). "Moreover, OMV treatment of BMM led to the release of large amounts of IL-1β and IL-18 in an MOI-dependent manner whereas infection with P. gingivalis only led to minimal amounts of these mediators being produced." (PMID 28824884, 2017). "We have shown that knockout of caspase b, presumably resulting in a decrease in il1β secretion results in less macrophages being recruited to sites of infection, but does not affect the early recruitment of neutrophils." (PMID 28747644, 2017). "This strain induced IL-1β levels from infected macrophages in a caspase-1-dependent manner similar to wt bacteria, suggesting that SpeB is not involved in caspase-1-independent processing of IL-1β during infection of BMDMs." (PMID 28720729, 2017). "Indeed, hyphae and muriform cells infection induced high levels of TNF-α, IL-1β and IL-6 during the disease establishment stage." (PMID 28355277, 2017). "IL-17A was predominantly secreted by γδT cells (especially the Vγ4+γδT subset), but not CD4+Th and CD8+Tc cells at the early stage of infection, and IL-1β and/or IL-23 were sufficient to induce IL-17A production by γδT cells." (PMID 28912779, 2017). "Consistent with regulation of the Aim2 inflammasome by POP2, IL-1β production by POP2 transgenic J774A.1 cells was reduced after infection with F. novicida and L. monocytogenes, but not after Salmonella Typhimurium infection." (PMID 28580947, 2017). "In the present study, proteomic and transcriptional analyses did not reveal induction of NLRP3 and IL-1β expression after infection of guinea pigs with H5N1 virus." (PMID 28418930, 2017). "The clinical evaluations and laboratory parameters (haemoglobin [Hb], white blood count [WBC], IL-6, IL-1b, TNF-alpha) did not reveal systemic signs of infection or blood loss." (PMID 27125302, 2016). "KSHV infection induces IFI16-mediated IL-1β and IFN-β secretion during de novo infection." (PMID 27764250, 2016). "Furthermore, we found a significant increase in the concentration of IL-1β and TNF-α in the brain of mice with low-grade CLP 3 days after surgery, indicating an infection-initiated neuroinflammation." (PMID 27270556, 2016). "Our data show that MOI 0.1 is efficient to induce early IL-1β and caspase-1 activation and that cytokine and chemokine kinetics induced by MOI 1 versus MOI 0.1 is different suggesting that intracellular pathways are regulated by infection dosages." (PMID 27833923, 2016).
infection (continued). "Deletion of ISW2 did not significantly alter the responses to infection of serum cytokines IL-17, IL-1β, GM-CSF and the chemokines MCP-1 and RANTES relative to that observed in infected WT mice." (PMID 27727302, 2016). "Interestingly, in the case of infection by O. tsutsugamushi, 2-APB significantly activated IL-1β production, which is known to be important for the activation of adaptive immune cells, namely antigen-specific T cells." (PMID 27472555, 2016). "Since MCs and serglycin proteoglycans may contribute to the pro-inflammatory cytokine signaling during infection, we analyzed the serum levels of the pro-inflammatory cytokines TNF-α and IL-1β, and the regulatory cytokine IL-10." (PMID 27267469, 2016). "No protein release of IL-1β by HPBCs was detected regardless of the model of infection, even after stimulation with LPS (data not shown)." (PMID 27446812, 2016). "While IL-1β and IFNα are not involved in the block to single-cycle infection, it is possible that cytokines released in response to R848 protect bystander monocytes as well as T cells which themselves do not respond to R848." (PMID 27905985, 2016). "However, significant increases in the transcription of goose IFNα, IFNγ, IL1β, and IL6 were all observed after infection with these two types of virus (TMUV and GPV) (P < 0.01; P < 0.01; P < 0.01; P < 0.01)." (PMID 27150912, 2016). "Moreover, the antiviral activity can be amplified by the chemoattractant function of the chemokines which recruit leukocytes to the site of infection and activate these cells to secrete the proinflammatory cytokines (TNF-α, IL-1β and IL-6)." (PMID 27538960, 2016). "Expression of several other innate immune related genes such as the β-defensin AvBD9 and chemokines RANTES and IL-8 in the lung and IL-1β and IL-6 in the spleen were not significantly altered by infection or D-CATH-2 treatment." (PMID 27229866, 2016). "Some of the genes with the highest robust CV had identifiable immune- and/or infection-related functions (e.g., IL1B, CXCR1), while others did not." (PMID 27658638, 2016). "Since A46 has been characterized as an antagonist of host IL-1 and TLR-signaling, quantifying the IL-1β secreted after activation of these pathways, by MVA infection, might be a way to measure the biological effect of presence/absence of A46." (PMID 27223301, 2016). "After 60 h of infection, at the more acute phase, the bacteria had induced a substantial increase in the expression of genes for most proinflammatory cytokines, including IFN-γ, IL-1β, IL-2, IL-6, IL-8, IL-22, and TNF-α, as well as genes for IL-10 and IL-4." (PMID 27357336, 2016). "In our analysis, we observe that a subset of these cytokines reported to be present in the serum also show transcriptional upregulations in PBMCs by 4 days post-infection (IL6, IL1B, IL1RN, CCL8, CXCL10) and by 7 days post-infection (CCL2, CCL3, CSF1, TNF, CXCL1, FAS and CXCL8)." (PMID 27595844, 2016). "We also identified differences between the responses of young and aged mice to infection, including four markers that were significantly elevated in young mice (IL-1β, IL-10, IL-13, eotaxin) but not aged or dam mice." (PMID 27936166, 2016). "Paradoxically, Il1b-/- mice were resistant to infection, unlike the invasive enteropathogens Salmonella and Shigella, which are lethal for Il1b-/- mice." (PMID 27732661, 2016). "We found that TNF-α and IL-1β levels were below the detection limit for most of the days after infection (data not shown) for both high dose (1000 TCID50) groups treated with oseltamivir either prophylactic or therapeutic regimen." (PMID 27110056, 2016). "To clarify the role of Dectin-2 in the host response to S. pneumoniae infection, we compared the production of proinflammatory cytokines and chemokines, such as IL-1β, TNF-α, IL-6, IFN-γ, IL-17A, and MIP-2, in BALF between WT and Dectin-2KO mice 12 h after infection." (PMID 26727976, 2016).
infection (continued). "Infection with IAV leads to activation of the Nlrp3 inflammasome in a process requiring the type I IFN-induced RNAse L/OAS system, while the virus actively suppresses IL-1β production and Nlrp3 activation via the NS1 protein." (PMID 27579026, 2016). "By qRT-PCR, we found that there were no obvious up-regulations in the expressions of IL-1β and IL-6 during the early phase infection of CK/SD/w3 and CK/SD/w4." (PMID 27446066, 2016). "Although the bacterial burdens did not change among the early and advanced phases of infection, IL-1β levels significantly differed." (PMID 27189736, 2016). "In addition, cytokine levels at the site of infection, as well as IFN-γ, IL-1β and IL-10 production by antigen-stimulated lymph node cells were similar among groups." (PMID 27056545, 2016). "IL1β is a major potent proinflammatory cytokine with pleiotropic effects on the immune system, which is widely produced in goose organs during GPV and TMUV infection." (PMID 27150912, 2016). "Although we do not further pursue the mechanism responsible for increased IL-1β release in Aim2-/- mice following Ft LVS infection in this report, this effect was consistently observed in all our experiments." (PMID 27926940, 2016). "Levels of IL-1β, IL-6, CCL2, CCL3 and CCL5, which are known to play an important role during HSE, were measured in brain homogenates using magnetic bead-based immunoassays prior to (day 0) and on days 6, 8 and 10 following infection." (PMID 27930721, 2016). "It is known that human IECs in the steady state do not express IL-1β mRNA, but they can produce it upon stimulation (infection, inflammation)." (PMID 25799280, 2015). "We hypothesize that CCR5 activation may function in an early and rapid response to infection, where virus coat protein or products of bacteria (such as hsp 70) trigger the induction of inflammatory genes such as iNOS, COX-2 and IL-1β." (PMID 26295266, 2015). "The serum concentration of IFNγ, TNFα, IL-10 and IL-6 only started to increase substantially on day 6 post-infection, and no apparent difference was observed in the serum levels of IL-1β." (PMID 25768944, 2015). "Finally, pigs surviving the infection with E75CV1 showed a very consistent signature characterized by the up-regulation of IL-23, IFN-γ and NFκB and the down-regulation of IL-1β and IL-4." (PMID 26589145, 2015). "Indeed, as compared with CP-deficient mice, the wild type mice produced significantly higher levels of proinflammatory cytokines: IL-1β, IL-6, and MIP-2 at 2 h, and all 6 cytokines at 12 h post infection." (PMID 26147796, 2015). "Also, the mRNA levels of iNOS and inflammatory cytokines, IL-1β, TNF-α, and IFN-γ, were upregulated after infection with E. papillata, whereas PPE significantly reduced the expression of these genes." (PMID 25654088, 2015). "So far, Mtb-induced phagosomal rupture has only been observed atlater stages of infection, i. e, 3–5 dpi, akinetic situation, which cannot explain the very early, ESX-1-dependent release oftype I IFNs or IL-1β, that requires recognition of mycobacterial components bythe host cytosolic sensors." (PMID 25658322, 2015). "Collectively, we here provide evidence that Leishmania major and mexicana parasites are able to dampen IL-1β secretion during initial stages of infection, rendering cells non-responsive towards stimulation of the NLRP3 inflammasome." (PMID 26114647, 2015). "Expectedly, infection of P.a (2.5×106 CFU/mice), resulted in a sharp increase in neutrophils associated with increased levels of KC, IL-6, TNFα, IL-1β and IL-12 in BAL fluids compared to non-infected mice." (PMID 25605549, 2015). "The expression of endocan is up-regulated in response to TNF-α or IL1-β in vitro, although the precise mechanism of endocan expression in infection has not been elucidated." (PMID 25894539, 2015). "Besides TNF-α, the induction of other cytokines including IL-6 and IL-1β was also observed in both Huh7 cells and PHH at 2 hours post-infection." (PMID 26023919, 2015).
infection (continued). "Some reports indicate that the role the inflammasome is dependent on the model for infection with a possible delay in the resolution of cutaneous lesions in the absence of IL-1β." (PMID 26114647, 2015). "In contrast, mice lacking IL-1β appeared to control the infection in its early stages, but eventually succumbed and were not rescued by administration of IFNγ." (PMID 25768794, 2015). "We therefore examined gene expression for several important interferon-related genes (IFNα2, IFNα4, IFNβ, IFNαβR, IFNγ, IFNγR, Irf3, Irf7, Mx1, Oas1, IFITM1, IFITM2), along with inflammasome-related genes IL-1β and NLRP3, and chemokines CCL5, CCL7, and CCL12 at d1 post-infection." (PMID 26110868, 2015). "Interestingly, the production of IL-1β was significantly increased by S. pneumoniae D39 infection, whereas treatment with NAC significantly reduced IL-1β production." (PMID 26683708, 2015). "H1N1pdm09 infection alone did not induce release of IL-1β or IL-6 PBMCs from either pregnant or non-pregnant women when compared to media." (PMID 25831059, 2015). "However, sufficient levels of IL-1β and TNF-α were produced in cultured murine macrophages by repeated infection with P. gingivalisin vivo." (PMID 26783845, 2015). "WNV also induces a dramatic increase in several pro-inflammatory cytokines such as tumor necrosis factor alpha (TNF-α) and interleukin (IL)-1β and chemokines such as CCl2 and CXCL10, which regulate leukocyte trafficking into the brain and neuronal death after infection." (PMID 26392176, 2015). "Real-time quantitative polymerase chain reaction showed that the expression of TLR3, TLR7, RIG-I, MDA5, IL-1β, IL-2, IL-6, IL-8, IFN-alpha, IFN-beta, IFN-gamma in the lungs was significantly greater than in the respective thymus genes during the early post infection stage." (PMID 26635752, 2015). "IL-1β, together with TNF-α and IL-6, are thought to be important proinflammatory mediators in initiating and maintaining the inflammatory response to pathogen and disease development during infection." (PMID 26052324, 2015). "However, the expression levels of IL-1β, IL-2, IL-8, IFN-alpha, and IFN-gamma were downregulated in the lungs following SS-10 infection at 72 hpi." (PMID 26635752, 2015). "Using cells only treated with IL-33 or cells only infected with HTNV as controls, the mRNA expression of IL-1β, IL-6, IL-8, CCL2, CCL20, CXCL1, CXCL2, and CX3CL1 was significantly induced in HUVECs prior to infection with HTNV (MOI = 1) for 48 h and then exposed to IL-33 (20 ng/ml) for 6 h." (PMID 25658420, 2015). "Ultimately, this translates into production of pro-inflammatory cytokines (e.g., IL-1β, IL-6, TNF-α, and IL-12p70) and chemokines (e.g., CXCL8, CCL2, CCL3, and CCL4), which are essential in combating infection by facilitating and enhancing phagocytosis and inflammation." (PMID 26580658, 2015). "In contrast, mice lacking IL-1 receptor or IL-1β, but not IL-1α, appeared to control the infection in its early stages, but eventually succumbed." (PMID 25768794, 2015). "Western blots indicated that protein production for IL-1β, S100A8, and S100A9 is significantly increased upon infection (lanes denoted by “I”), which confirms the RNA-seq data for the genes encoding these proteins and further validates the RNA-seq data as a whole." (PMID 25901897, 2015). "In the later stages of infection, other inflammasomes, such as NLRP3, activated by commensal bacteria, may play a more important role in the regulation of mucosal IL-1β." (PMID 26269452, 2015). "However, during infection with Ft LVS, activation of TLR2 and the inflammasome significantly boosts this response in an IL-1β-dependent fashion." (PMID 25768794, 2015). "In our model, although IL-1β and IL-23 were also induced upon infection, we did not obtain statistically significant differences between the unstimulated/stimulated MФ." (PMID 26125939, 2015).